STAT3 (signal transducer and activator of transcription 3)
Diseases named in the same sentence as STAT3 in open-access papers (continued):
Sharing a sentence is not in itself a finding about the gene and the disease.
glioblastoma (continued). "EGFRvIII has also been detected in the nucleus of normal glial cells and primary glioblastomas, where it forms an oncogenic complex with STAT3 to mediate EGFRvIII-dependent glial transformation." (PMID 22520625, 2012). "Quantitative phosphorylation events focused on signal transducer and activator of transcription 3 (STAT3)/interleukin 6 (IL6)/hypoxia-inducible factor 2α (HIF2α) autocrine loop were also reported regarding glioblastoma stem cells." (PMID 22912867, 2012). "In this study, we demonstrate that human glioblastoma tumors failing bevacizumab have an increase in the mean percentage of p-STAT3-expressing cells compared to samples taken from patients failing non-antiangiogenic therapy containing regimens." (PMID 23013619, 2012). "We examined the effects of LLL12 on medulloblastoma and glioblastoma cell lines which express phosphorylated STAT3." (PMID 21526200, 2011). "FLLL32 was found to be more potent than some existing STAT3 inhibitors, including Stattic, S3I-201, and curcumin in colorectal, glioblastoma, multiple myeloma, rhabdomyosarcoma, and liver cancer cell lines." (PMID 21443800, 2011). "Cell Viability assays were run on several human medulloblastoma and glioblastoma cells lines which express elevated levels of phosphorylated STAT3 in order to assess LLL12's inhibitory effects." (PMID 21526200, 2011). "Here we show that LLL12 inhibits STAT3 phosphorylation, decreases cellular viability, downregulates STAT3 target gene and induces apoptosis in medulloblastoma and glioblastoma cell lines." (PMID 21526200, 2011). "LLL12 was able to inhibit STAT3 phosphorylation, decrease cell viability and induce apoptosis in medulloblastoma and glioblastoma cell lines with elevated levels of p-STAT3 (Y705)." (PMID 21526200, 2011). "Two cell lines which express lower levels of p-STAT3 (Y705), D283 (medulloblastoma) and U373 (glioblastoma), were used to assess LLL12's specificity." (PMID 21526200, 2011). "We found that LLL12 inhibited the transcription of the STAT3 downstream target genes, cyclin D1, survivin, Bcl-2, and Bcl-xL in medulloblastoma and glioblastoma cell lines." (PMID 21526200, 2011). "Recent studies have demonstrated that over-activation of STAT3 is observed in several human malignant tumors and cell lines, including glioblastoma." (PMID 21906308, 2011). "Similar to our study, Gariboldi and colleagues reported that NVP-AEW541, a IGFR1 inhibitor, disrupted IGF/STAT3/HIF1 pathway in human glioblastoma cells." (PMID 21731766, 2011). "IL-6, whose production is stimulated by hypoxia and elevated in glioblastoma cells, stimulates the activation of the transcription factor STAT3." (PMID 21655185, 2011). "Our results showed that FLLL32 was a potent inhibitor in inhibiting STAT3 phosphorylation and STAT3 DNA binding activity in human glioblastoma cell lines." (PMID 20712901, 2010). "Our results suggest that FLLL32 is a potent therapeutic agent for multiple types of cancer cells expressing constitutive STAT3 signaling including multiple myeloma, glioblastoma, colorectal and liver cancer cells." (PMID 20712901, 2010). "Overexpression of IL-6, an upstream regulator of STAT3 is also detected in glioblastoma and is a marker of malignancy." (PMID 20712901, 2010). "The persistent activation of STAT3 is in part, also attributable to an autocrine action of IL-6 in the glioblastoma cells." (PMID 20712901, 2010). "Higher levels of STAT3 have been demonstrated in CSCs isolated from liver, bone, cervical and brain cancers, and furthermore treatment of putative glioblastoma stem cells (GBM-SC) with Stattic results in a dramatic reduction in their formation." (PMID 20929579, 2010). "Many clinical cases of glioblastoma and glioblastoma cell lines express constitutively activated STAT3." (PMID 19127268, 2009). "STAT-3 has been found to be constitutively activated in 50-90% of all malignant tumors, including 53% of anaplastic astrocytomas and 53% of glioblastomas." (PMID 19900287, 2009).
glioblastoma (continued). "Activation of STAT3 has also been shown to enhance immune tolerance in glioblastoma, enabling cancer cells to evade immune surveillance." (PMID 19127268, 2009). "Our results show that, LLL-3 inhibits STAT3 activities, inhibits cell viability, and induces apoptosis in U87, U251, and U373 glioblastoma cells." (PMID 19127268, 2009). "Persistent activation of the signal transducer and activator of transcription 3 (STAT3) signalling has been linked to oncogenesis and the development of chemotherapy resistance in glioblastoma and other cancers." (PMID 19127268, 2009). "Based on our findings, LLL-3 appears to be a potential therapeutic agent for human glioblastoma cells and possibly other tumours that have constitutively active STAT3." (PMID 19127268, 2009). "Serotonergic medications may modulate IL-6, activating STAT3 and NF-κB to promote glioblastoma proliferation." (PMID 40894022, 2025). "Overall, these findings suggest that quercetin has potential as an anticancer agent for glioblastoma treatment, potentially improving the cancer microenvironment and offering a new therapeutic strategy for managing glioblastoma by targeting the Axl/IL-6/STAT3 signaling pathway." (PMID 41009025, 2025). "Exosome-derived IL-6 from human glioblastoma (GBM) cells may trigger autophagy in macrophages by activating the Signal Transducer and Activator of Transcription 3 (STAT3) signaling at least in vitro." (PMID 40191733, 2025). "Exosomes’ ability to cross the BBB makes them particularly promising for glioblastoma therapy, where OC’s STAT3 inhibition (refer below for details) could be maximized." (PMID 40564985, 2025). "In particular, NF-κB and COX-2 suppression could mitigate microglia-driven IL-6/STAT3 signaling, which is known to contribute to the maintenance of glioblastoma stemness." (PMID 40564985, 2025). "Additionally, in glioblastoma models, tumor-derived exosomal circPRKD3 suppresses malignant progression by inhibiting STAT3 (signal transducer and activator of transcription 3) signaling and remodeling the immunosuppressive tumor microenvironment." (PMID 41049614, 2025). "Upon methylation of STAT3 via EZH2 in glioblastoma stem-like cells, STAT3 activity was enhanced." (PMID 38183103, 2024). "Additionally, it was found that STAT3 suppression reduced the proliferation of tumor spheres and as well as the expression of the neural SCs genes Nestin and Olig2 in glioblastoma cells." (PMID 39309691, 2024). "TSPAN6 knockdown statistically inhibited the activation of STAT3 in glioblastoma cells." (PMID 38725860, 2024). "Indeed, glioblastoma cells with high level of TSPAN6 statistically enhanced STAT3 activation of HUVEC cells." (PMID 38725860, 2024). "Overexpression of PIAS3 reduces the STAT3 transcription in glioblastoma and ovarian cancer." (PMID 38590645, 2024). "Therefore, the JAK/STAT3 signaling cascade has been considered a prime therapeutic target for glioblastoma intervention." (PMID 39153914, 2024). "Ultimately, EZH2 directly regulates STAT3, and its inhibition may impair key signaling pathways that promote tumor growth and maintain a stem-like tumor cell population in glioblastoma." (PMID 38183103, 2024). "Therefore, the JAK/STAT3 pathway has been considered an ideal target for the treatment of glioblastoma." (PMID 39153914, 2024). "We confirmed the role of Stat3 in improving the poor progression and prognosis of glioblastoma." (PMID 39459502, 2024). "The dual role of STAT3 in the development of human cancers was first examined in glioblastomas." (PMID 38339245, 2024). "In the context of glioblastoma, STAT3 is crucial for tumor growth and progression." (PMID 39153914, 2024). "Still, a significantly increased expressions of STAT3 and pSTAT3 were found almost universally in repeated resections of most analyzed patients, thereby suggesting a possibly pronounced role of this molecule in recurrent glioblastoma." (PMID 38654280, 2024).
glioblastoma (continued). "Additionally, it has been shown that EZH2 can enhance the STAT3 signaling pathway in glioblastoma and oral squamous cell carcinoma." (PMID 39120328, 2024). "To explore the mechanism of TSPAN6 in promoting angiogenesis in TME, we hypothesized that glioblastoma cells overexpressing TSPAN6 might induce STAT3 activation of vascular endothelial cells." (PMID 38725860, 2024). "In addition, subsequent studies on the role of STAT3 in the context of glioblastoma hypoxia demonstrated opposing effects of its deletion on cell viability as well as the expression of hypoxia and EMT markers." (PMID 38654280, 2024). "Activation of STAT3 signaling promotes self-renewal and tumorigenesis of glioblastoma stem cells." (PMID 38495483, 2024). "Meanwhile, STAT3 knockdown also reversed TSPAN6 activated EMT progress of glioblastoma cells." (PMID 38725860, 2024). "BCL3 regulation of STAT3 expression has been described in cervical, and glioblastoma cell lines, where shRNA knockdown of BCL3 resulted in decreased STAT3 and in the latter, pSTAT3 protein levels, while overexpression of BCL3 promoted the increase in STAT3 protein levels in both cell types." (PMID 38195591, 2024). "Although results of this work did not reveal in recurrent glioblastoma samples generally unanimous and distinct factors characteristic for LTS patients, STAT3 and its expression appears to be a feasible point for evaluation of existence and roles of hypoxia in recurrent glioblastoma." (PMID 38654280, 2024). "As we expected, the direct interaction between CDK5RAP3 and STAT3 could also be verified in glioblastoma cells using immunoprecipitation." (PMID 38725860, 2024). "Our analysis of predicted differentially expressed miRNA target genes showed gene enrichment in critical cancer pathways linked to tumorigenesis, including the RAS, STAT3, FoxO, MAPK, PI3K-Akt signalling pathways, as well as glioblastoma invasiveness signalling." (PMID 38455766, 2024). "Through the signal transducer and activator of transcription 3 (STAT3) pathway, angiogenesis in the microenvironment of glioblastoma is promoted, thereby alleviating the survival pressure of cancer cells under hypoxia conditions and deepening the deterioration of cancer cells." (PMID 39366930, 2024). "This heterogeneity was subsequently confirmed in other employed models (primocultures derived from glioblastoma tissue resections, cryopreserved tumor specimens, stabilized glioblastoma cell line in vitro and in vivo) and concerned, in particular, STAT3 expression which remained stable." (PMID 38654280, 2024). "It is also possible that hypoxia and STAT3 operate in a larger tumor context and their individual roles are not sufficiently distinctive and standalone to universally characterize glioblastoma biology in LTSs in a similar manner to other analyzed markers, signatures or profiles." (PMID 38654280, 2024). "Also, microRNA-21 was proven to enhance carcinogenesis through STAT3, and reduced expression of both hTERT and STAT3 as well as slowed tumor growth were observed when microRNA-21 was knocked down in murine glioblastoma xenografts." (PMID 39683343, 2024). "In addition, STAT3 inhibitor niclosamide successfully reversed TSPAN6 activated EMT progress of glioblastoma cells." (PMID 38725860, 2024). "However, it is proposed in glioblastoma that high MSH6 promotes aggressive cell phenotypes more directly by acting through a MSH6-CXCR4-TGFβ1 feedback loop that regulates p-STAT3/Slug and p-Smad2/3/ZEB2 signalling pathways." (PMID 36482191, 2023). "The lncRNA HOXD‐AS2/STAT3 feedback loop attenuates temozolomide sensitivity, indicating that this pathway may offer novel therapeutic target for treatment of glioblastoma." (PMID 37308741, 2023). "In addition, it has been reported that in glioblastoma, the STAT3 pathway is a key molecular hub in tumor-mediated immunosuppression." (PMID 36977736, 2023).
glioblastoma (continued). "Moreover, TRIM24 has been shown to drive tumorigenesis via recruiting signal transducer and activator of transcription 3 (STAT3) in glioblastoma." (PMID 38129408, 2023). "In addition, this work demonstrated that RSV inactivated p-STAT3, promoting the differentiation of glioblastoma-initiating cells." (PMID 38026933, 2023). "Likewise, highly expressed GBP2 contributed to the invasion of glioblastoma multiforme through Stat3/FN1 signaling pathway." (PMID 37622120, 2023). "Glioblastoma CSC-derived exosomes can stimulate M2 polarization, programmed death-ligand 1 (PD-L1) expression, and the production of monocyte chemotactic protein 3 (MCP-3) and CXCL1, which promote myeloid cell recruitment, through the STAT3 pathway in glioblastoma." (PMID 36672697, 2023). "Because 15α-MP inhibits pSTAT3-Tyr705 in human glioblastoma cells and recent animal tests support its anticancer effect against glioblastoma, activated STAT3 may be an antitumor target of 15α-MP." (PMID 36923251, 2023). "Additionally, RXFP1-CTRP8 promotes actin cytoskeletal remodeling and filopodia formation through STAT3 signaling, further enhancing glioblastoma migration." (PMID 37033981, 2023). "Moreover, JSI-124 exhibits the capacity to restrain the proliferative behavior of glioblastoma cells by focusing on the consistently active STAT3 signaling route." (PMID 38001999, 2023). "The interaction between EZH2 and STAT3 has also been reported in glioblastoma and colon carcinomas." (PMID 37664059, 2023). "CA has been reported as a STAT3 inhibitor in OvCa, glioblastoma, and osteosarcoma." (PMID 37173951, 2023). "Here, we show a hitherto unknown role of STAT3 in sensitizing glioblastoma cells to excessive autophagy induced with the repurposed drug pimozide." (PMID 35053502, 2022). "Lastly, considering that STAT3-activity has been previously associated with the mesenchymal subtype of GBM we analyzed if spheroid cultures, so called glioblastoma stem-like cells (GSC), representing the different molecular subtypes show differential sensitivity to Pimo." (PMID 35053502, 2022). "In conclusion, the PIKE-A/STAT3/FTO/SDHA pathway might play a pivotal role in glioblastoma conformation, progression, and proliferation." (PMID 36232604, 2022). "In addition to the anti-proliferative action, the inhibition of the JAK/STAT3 signaling pathway induced by curcumin is strongly correlated with a significant inhibition of cell migration and therefore of invasiveness of the glioblastoma." (PMID 35328780, 2022). "Interestingly, studies have revealed that niclosamide treatment leads to the downregulation of MAPK/ERK, and STAT3 prosurvival signal transduction pathways to further reduce human glioblastoma U-87 MG cell viability." (PMID 35008910, 2022). "Additionally, patients with glioblastoma have constitutively activated STAT3 and secreted IL-6 levels that are correlated with tumor grade." (PMID 36193062, 2022). "In the present study, we found that exogenous of STAT3 in PIKE-A knockdown glioblastoma cells could rescue the decreased SDHA expression." (PMID 36232604, 2022). "For example, glioblastoma stem cell-derived exosomes upregulate the expression of PD-L1 in human monocytes, which may correlate with STAT3 phosphorylation." (PMID 35090497, 2022). "Knockdown of STAT3 expression by RNAi was found to suppress growth and induce apoptosis and differentiation in glioblastoma stem cells, and WP1006, a selective inhibitor of JAK, was shown to be inhibitory against malignant glioma cell growth both in vitro and in vivo." (PMID 35281458, 2022). "EZH2 can also methylate STAT3 and increase its activity in glioblastoma stem cells." (PMID 36612203, 2022).
glioblastoma (continued). "Collectively, these observations indicated that interfering with the HA pathway could promote M1 macrophages polarization via activation of STAT1 phosphorylation and inhibited M2 macrophages polarization via impairment of STAT3 phosphorylation in glioblastoma." (PMID 35410993, 2022). "The dysregulated STAT3 signaling is involved in glioblastoma development." (PMID 35538578, 2022). "Recent studies have explored the role of GBP2 on carcinogenesis and found that GBP2 could enhance the invasive ability of glioblastoma via the GBP2/Stat3/FN1 signal cascade." (PMID 35356208, 2022). "STAT3 is activated in glioblastoma tumors and glioblastoma-derived cell lines." (PMID 36362294, 2022). "EZH2 can also methylate STAT3 to increase STAT3 activity in glioblastoma stem cells." (PMID 36612203, 2022). "STAT3 upregulation in glioblastoma has been demonstrated in various studies." (PMID 35328780, 2022). "Indeed, following PLCβ1 silencing, it is also shown in our data, an increased activation of Stat3 pathway, which is a well-defined oncogenic transcription factor that plays a key role in tumor resistance and aggressive cancer progression in glioblastoma." (PMID 35303162, 2022). "GBP2 has been reported to increase glioblastoma invasiveness through the Stat3/fibronectin pathway." (PMID 36186425, 2022). "GBP2 promotes glioblastoma invasiveness through the Stat3-mediated immune pathway." (PMID 36186425, 2022). "Therefore, cinobufagin blocks EGFR/STAT3 signaling in glioblastoma and shrinks brain tumors, elongating nude animal survival." (PMID 34925034, 2021). "In the present study, canine osteosarcoma, human osteosarcoma and glioblastoma cell lines, exhibited similar response to single CT treatment and cancer cell death was further enhanced by introducing another STAT3/5 inhibitor, a proteasome inhibitor drug, and an EGFR/ErbB2 inhibitor." (PMID 33544704, 2021). "Importantly, genetic or pharmacologic targeting of CD109/STAT3 axis sensitized the GSCs to chemotherapy, suggesting that targeting CD109/STAT3 axis has potential to overcome therapy resistance in glioblastoma." (PMID 33986188, 2021). "CD109-silenced GSCs showed markedly reduced p-STAT3 levels compared with the nontargeted controls independently of the glioblastoma subtype, thus verifying the observed association between CD109 and p-STAT3 in the patient samples." (PMID 33986188, 2021). "Importantly, a recent report also demonstrated that the ancient anti-inflammatory drug ACT001 reduces the expression of PD-L1 in glioblastoma by inhibiting the phosphorylation of STAT3." (PMID 34503167, 2021). "Our results suggest that targeting the CD109/STAT3 axis in GSCs could provide means to overcome therapeutic resistance and improve treatment efficacy in patients with glioblastoma." (PMID 33986188, 2021). "TROP2 activates the JAK2/STAT3 pathway to promote metastasis in glioblastoma cells." (PMID 34067437, 2021). "Radix Salviae could inhibit the proliferation and invasion of human glioblastoma by regulating STAT3, Akt, and IKB signaling pathways." (PMID 35154340, 2021). "The anticancer activity of Qu has been found through the inhibition of the signal transducer and activator of transcription 3 (STAT3).Qu has been reported to be capable of reducing glioblastoma cell proliferation and migration via the inhibition of STAT3 activation." (PMID 33804548, 2021). "Targeting STAT3, which is involved in maintaining an immunosuppressive environment in glioblastoma and is consistently activated in a variety of tumors, is an alternative therapeutic strategy for glioblastoma." (PMID 34485282, 2021). "Furthermore, STAT3 was shown to be highly expressed in glioblastoma stem cells (GSCs), which are tumor cells with self-renewing properties that contribute to tumor initiation and therapeutic resistance." (PMID 34359668, 2021).